CD8A (CD8 subunit alpha)
Diseases named in the same sentence as CD8A in open-access papers (continued):
Sharing a sentence is not in itself a finding about the gene and the disease.
tumor (continued). "To ensure that the influence of our TEX signature was associated with survival independently of overall immune and T cell infiltration, we also included gene expression of CD8A, CD3G, and PTPRC in addition to patient age, tumor grade, tumor size, and LN status." (PMID 35132960, 2022). "In secondary lymphoid tissues such as the spleen and lymph nodes, mouse cDC1s highly express CD8α on their surface, whereas nonlymphoid tissue–resident mouse cDC1s, including tumor-resident cells, express integrin-αE (CD103)." (PMID 35454882, 2022). "The density of α-smooth muscle actin (α-SMA) (a marker of TAFs) and CD31 (a marker for tumor vasculature) in the nanovaccine and anti-CTLA-4 mAb groups was lower than that of the PBS group, whereas the density of CD8 (a marker for CD8+ T cells) was higher than that of the PBS group." (PMID 34875483, 2022). "Our results also indicate that, in the absence of CD8α+ cDC1s, pre-cDC1s induce a more potent anti-tumor response in the presence of limited Ag." (PMID 35980974, 2022). "Furthermore, we found invariably positive correlations between CD8A expression and CTL levels of patients in these cohorts, such observations corroborated the established role of CD8A in promoting CTL-mediated tumor killing." (PMID 36035168, 2022). "Regardless of the precise underlying molecular mechanism, for the first time we observed tumor clearance in the bone marrow by TEG011_CD8α, but not by TEG011 alone." (PMID 34759930, 2021). "Based on bulk RNA data from the TCGA cohort, the highest levels of wild-type CYSLTR2 expression were observed in tumours with an inflammatory phenotype as shown by their immune gene expression signature (high expression of CD14, CD163 [monocytes/macrophages] and CD3D, CD8A [T cells])." (PMID 33588787, 2021). "Similarly, high DC1 LUSC and normal tissues had higher CD8A and CD8B expression than low DC1 infiltration tumor samples." (PMID 34422829, 2021). "Supporting this, the intratumoral application of TriMix mRNA not coding for TAAs led to the activation of CD8a+ DC, T cells and reduced tumor growth in various murine tumor models (E.G7-OVA, P815, A20, and TC-1)." (PMID 33722265, 2021). "Depleting CTLs with anti-CD8α (YTS 169.4) antibody in GLUT1ΔmΦ mice resulted in significantly larger tumors compared to the isotype control treated mice, indicating that CTLs are also key to controlling tumor growth in GLUT1ΔmΦ mice." (PMID 34198548, 2021). "CD8α ALN-1 synergizes with a neovasculature-targeted tumor necrosis factor (TNF) AcTakine, leading to complete tumor destruction and formation of immunological memory that protects against secondary tumor challenge." (PMID 34772757, 2021). "However, both AURKA and AURKB expression were significantly inversely correlated with markers for T-cell infiltration of the tumor: CD3E, CD4, CD8A, LCK, PDCD1 and IFNG." (PMID 33123754, 2021). "CD8α ALN-1 strongly shifted the phenotype of the infused T cells towards an effector phenotype, characterized by a CD44+CD62L- profile and T-bet expression, in the TDLN and the tumor." (PMID 34772757, 2021). "Cyclophosphamide also impacts induction of antitumor immunity in vivo: it promotes expansion of CD8a+ DCs through induction of endogenous IFN-I and induces immunogenic tumor cell death, stimulating tumor infiltration and the engulfment of apoptotic material by DC to cross-prime CD8+ T cells." (PMID 33766090, 2021). "The CD8α+ (mouse) and CD141+ (human) type 1 cDC (cDC1) subtype efficiently presents major histocompatibility complex (MHC) class 1 antigens to CD8+ T cells, initializing potent anti-tumor immune responses in “hot” tumors." (PMID 34685652, 2021). "Moreover, CD163 expression was positively correlated with most gene markers of these tumor-infiltrating immune cells in both the TCGA and CGGA cohorts, including CD8A, CD8B, STAT6, STAT5A, and PDCD1." (PMID 34395626, 2021).
tumor (continued). "CXCR3 mAb significantly prevented activated CD8α+ T cells from increasing in tumors, but not in lymph nodes, as a result of the anti-PD-L1 mAb treatment and significantly attenuated the tumor growth inhibition of the anti-PD-L1 mAb." (PMID 34230534, 2021). "Conventional T cells included conventional CD4+ T cells (cluster 4 in Paratumor and cluster 3, 8, 11 in Tumor; CD4+), regulatory T cells (cluster 8 in Paratumor, and cluster 5 in Tumor; FOXP3+), CD8+ T cells (cluster 2, 5, 10 in Paratumor, and cluster 0, 1, 2 in Tumor; CD8A+)." (PMID 33429363, 2021). "As a monotherapy, CD8α ALN-1 showed a modest effect on tumor growth, which was absent in mice that received WT IL-1β or untargeted BcII10 ALN-1." (PMID 34772757, 2021). "CD8A expression values from tumors were not correlated with levels of tumor-reactive CD8 T cells, indicating that the majority of present CD8+ cells are part of an unspecific immune response." (PMID 34210820, 2021). "Additionally, GO-Y030-treated tumor models tended to have more IFN-γ and TNF-α production from CD8α+ cells in tumor-infiltrating lymphocytes." (PMID 34248973, 2021). "In contrast, using anti-chicken CD8αβ monoclonal antibody to deplete CD8 T cells resulted in partial CD8α+ T cells depletion leading to increased tumor incidence in only monovalent (SB1 or HVT) but not bivalent (SB1+HVT)-immunized chickens." (PMID 33659011, 2021). "Further analysis of the flow profiles using standard gating approaches demonstrated that in 2/4 controls, approximately 30% of CD8α+, TRCβhi, NK1.1− T cells were positive for PD-1, the other two were similar to the treated tumours and >90% strongly PD-1 positive." (PMID 34359633, 2021). "To evaluate these hypotheses, we performed immunocytochemistry of 67NR and 4T1 tumours isolated from wild-type BALB/c mice using antibodies to CD8a and CD61 to stain CD8+ T cells and platelets, respectively." (PMID 33795809, 2021). "cDC1 cells in the tumor expressed the dermal marker Cd103 (Itgae), whereas their LN counterparts expressed Cd8a, a marker of LN resident populations, indicating that these cells did not migrate from the tumor." (PMID 32433953, 2020). "Zhu also discussed approaches to modify the hinge and transmembrane regions of CD8α in a CAR-T construct, in order to decrease the risk of CRS without compromising the anti-tumor efficacy of the modified CAR-T cell." (PMID 32245497, 2020). "Considering the ideal characteristics of DCs for eliciting a strong anti-tumor immune response referred to above, cDC1, particularly CD141+XCR1+ DCs (the homologues of murine CD8α+ DCs), besides being highly proficient in executing cross-presentation, produce large amounts of IL-12 and IL-15." (PMID 32075343, 2020). "This may explain the previously noted positive correlation between IL-32 expression and individual genes indicative of lymphocyte infiltration, such as CD3E, CD8A, and IFNG, in bulk tumor samples." (PMID 32841222, 2020). "Across 33 tumor types, CD274 and CD8A had broader positive correlations with m6A regulators." (PMID 33585244, 2020). "Finally, we investigated the connection between tumor grades and hub genes, in which LCK, CD2, CD3D, IFNG, CD8A, and CCL5 showed significant correlation with different tumor grades (p < 0.05), with grade increase corresponding to increased gene expression." (PMID 32081834, 2020). "In the case of anti-CD19 CAR T cells, human CD8α hinge and transmembrane molecules did not promote efficacies differently against tumor xenografts but induced lower cytokine levels compared with CD28 hinge and transmembranes." (PMID 33322408, 2020). "Although resident CD8α+ cDC1s may also be involved, migratory CD103+ cDC1s have unique abilities in tumor-antigen cross presentation." (PMID 32486257, 2020). "Besides, CD274, CD8A, GZMA, and PRF1 were positively correlated with the stromal score or immune score in almost all 33 tumor types." (PMID 33585244, 2020).
tumor (continued). "Specifically, murine CD8a+CD103+BATF3+CLEC9A+XCR1+ cDC1s have been demonstrated to have a critical role in the cross-presentation of tumor antigens and are generally thought to be indispensable in the development of host anti-tumor immune responses." (PMID 31921140, 2019). "In addition, the tumor-to-blood ratio of 89Zr-DFO-IgG2b was 1.9 ± 0.68 and significantly lower than that of control (p=0.0001) and CD8a+ depleted (p=0.0024) mice." (PMID 31754392, 2019). "The expression specific for tumour cells and CD8+ T cells estimated using RESPECTEx were in broad agreement with mean expression levels in MKI67+ single cells (for tumour) and CD8A+ single cells (for CD8+ T cells), confirming the validity of inferences by the RESPECTEx pipeline." (PMID 30624727, 2019). "All OS tumours had CD8A gene expression of varying degrees suggestive of CD8+ T-cell infiltration." (PMID 30674975, 2019). "Given the key role of tumor‐infiltrating lymphocytes (TILs) in BC, and the clustering neighbors to CD8A (as marker of CD8+ TILs), we performed a correlation analysis using CD8A protein values as a proxy reference of CD8+ TILs." (PMID 30451357, 2019). "Although CD8α and CD28 spacers have been extensively utilized in numerous clinical anti-CD19-CAR trials demonstrating potent anti-tumor efficacy, the impact of these hinges on CAR T cell performance has not been thoroughly investigated as of yet, thus their use remains largely empirical." (PMID 31108883, 2019). "Within tumor-draining lymph nodes, CD103+ cDC1s transfer a fraction of fluorescently labeled material to other antigen-presenting cell populations, including resident CD8α+ cDC1s." (PMID 30352680, 2018). "We analyzed the immunological components in the tumor microenvironment of STS and found that the components of the antitumor immune response in STS were mainly CD3E/CD4/CD8A-labeled T cells, CD57-labeled NK cells, and CD45RO-labeled memory T cells that can secrete IFN-γ." (PMID 29896199, 2018). "Specifically, it has been demonstrated that the conditional deletion of genes involved in type I IFN receptor (IFNR) signalling in the CD8α+ DC compartment significantly affects CD8+ T-cell priming and tumour rejection, thus ascribing to CD8α+ DCs a crucial role in anti-tumour immunity." (PMID 28404796, 2017). "Recent reports showed that incorporating GM-CSF, CpG and tumor antigens in PLG matrices efficiently attracted and stimulated both conventional DC (CD11c + CD11b + and CD11c + CD8a+) and plasmacytoid DC, resulting in superior immune responses (Th1 and CTL) against B16 melanomas in mice." (PMID 27660710, 2016). "In addition, using a neutralizing antibody against CD8α, we tested the consequences of a cytotoxic T lymphocyte (CTL) response on tumour growth." (PMID 27272654, 2016). "In the tumor bed of low- and high generation xenografts which underwent rejection, ED1+ macrophages and microglia were numerous, together with CD4+ and CD8a+ lymphocytes." (PMID 26291724, 2015). "We found that both absolute numbers and percentages of immature CD8α+ non-plasmacytoid DCs are increased to a greater extent following tumor inoculation in mice at ST compared to TT." (PMID 24575090, 2014). "The percentage of CD86− mature CD8α+ non-plasmacytoid DCs decreased at ST but not TT following tumor inoculation." (PMID 24575090, 2014). "Absolute numbers of CD86− mature CD8α+ non-plasmacytoid DCs increased following tumor inoculation in mice at ST but not TT." (PMID 24575090, 2014). "Interestingly, ALT-803 alone resulted in similar tumor reduction and production of urinary IL-1α, IL-1β and RANTES, which also led to the activation and proliferation of CD8a+ T-cells." (PMID 24896845, 2014). "Although the CD8α+ DCs were able to promote cross-priming of CD8+ T cells, there was a lack of expansion of the primed tumor antigen-specific CD8+ T cells." (PMID 24348481, 2013).
tumor (continued). "In accordance with this NK-like phenotype and as previously reported, CD8α+ and DN iNKT cells displayed more potent cytotoxicity than CD4+ iNKT cells against a number of CD1d+ tumor cell lines, with consistently higher proportions expressing cell-surface CD107a and killing target cells." (PMID 22174854, 2011). "For instance, Murphy and colleagues demonstrated that CD8α+ DCs were absolutely required for the generation of protective tumor-specific CTL using transgenic mice lacking expression of the transcription factor Batf3." (PMID 20976125, 2010). "The total number of CD45+ tumor infiltrating immune cells increased 10 d after intratumoral delivery of Ad-Flt3L and Ad-TK (p<0.001), as did the numbers of CD4+ T cells (p<0.001) and CD8a+ T cells (p<0.001)." (PMID 18431473, 2008). "Finally, we examined the spatial distribution of key tumor microenvironment markers such as CD8A, PD-L1, FOXP3, CD163, and VEGFA, further confirming that TMErisk genes aggregate in the tumor center and recruit immune cells, forming an immune hub (Figures 6G1, G2, G3, G4, G5)." (PMID 40104502, 2025). "Tumor bulk RNA-Seq data highlighted that the tumor expression of 5/32 genes (IRF1, IKZF1, SPI1, SH2B3, LAT) was each strongly correlated (Spearman’s ρ > 0.5) with at least one intra-tumor T/myeloid cell infiltration marker (CD4, CD8A, CD11B, CD45) in every one of the cancer types." (PMID 40428397, 2025). "Specifically, irradiation reduced extracellular matrix deposition and enhanced tumor cell apoptosis (evidenced by increased cleaved caspase-3 and cytosolic PCNA) while PD-1 blockade stimulated robust inflammatory responses, in particular, expansion of CD8α+ T cell infiltration." (PMID 41208884, 2025). "Furthermore, antigen-presenting molecules and immune molecular interactions, such as those between HLA-A, HLA-B, HLA-C, HLA-E, and HLA-F with CD8A and CD8B, appeared to be significantly up-regulated in tumor tissues, while their presence in normal tissues was comparatively diminished." (PMID 40723292, 2025). "Additionally, the tumor sample contained various other cell types, including epithelial cells (EPCAM+), pStr (MKI67+) CD4+T cells (CD4+), CD8+ T cells (CD8A+), macrophages (CD68+), and regulatory T cells (FOXP3+), which were further validated by our single-cell data." (PMID 39676856, 2024). "Next, in PAN02 bilateral subcutaneous tumor models, GN + OBP-702 significantly suppressed the growth of not only OBP-702-injected tumors, but also OBP-702-uninjected tumors, and this anti-tumor activity on uninjected tumors was significantly reduced by anti-CD8α injection." (PMID 38316993, 2024). "To determine whether iCD8α+ NK cells retained their enhanced functionality over longer time periods, we injected sorted CD8α+ and CD8α– CD56dim NK cells into NSG mice, infused them with K562 tumor cells the following day, and supported this with i.p. injections of IL-15." (PMID 38805302, 2024). "Additionally, at an in vivo level, CD8α+ and CD11b+ DCs from draining lymph nodes (DLNs) of B16-OVA- or MC38-OTIp-tumour-bearing Ythdf1−/− mice showed a substantially augmented cross-priming capacity as compared with those collected from the wild mice when both co-cultured with OT-I T cells." (PMID 38136940, 2023). "Moreover, many genes related to an accumulation of T cells (Cd8a, Cd3e, Cd4), inflammations (Cxcl9, Tnf, Ifng), and a subset of M1-macrophage (Ciita, Nos2, Cd86) have elevated in anti-PD-1 antibody-treated IL-34KO CT26 tumor." (PMID 36798830, 2023). "However, the ratio of CD4+/CD8a+ T cells was lower in both PLD and PLAD treated mice, which may be indicative of less immunosuppression in the tumor microenvironment." (PMID 36105861, 2022). "The clustering of T/NK cells of the tumor environment revealed 5 main populations, including NK/NKT subtype (GNLY and TRDC), γδ T cells (GNLY, TRDC, and CD3D), CD4+CD8+ T cell subtype (CD3D, CD8A, and CD4), CD8+ T cells (CD3D and CD8A), and CD4+ T cells (CD3D and CD4)." (PMID 35907904, 2022).
tumor (continued). "In tumor patients with a relatively high level of neutrophils, T cell immune response is often reduced, as represented by the reduced expression of cytotoxic T cell genes including CD8A, CD8B, GZMA, and GZMB, the reduced number of CD3 + CD8 + cells, and the reduced expression of IFN-γ related genes." (PMID 36275807, 2022). "Results revealed that dying tumor cells undergoing ICD could be further filled with adjuvant nano-depots to successfully initiate antigen cross-presentation by dendritic cells and activate potent antigen-specific CD8α+ T cells in mice model bearing CRC." (PMID 36341334, 2022). "Another study also demonstrated that mice lacking IFNAR1 in DCs could not reject highly immunogenic tumor cells and that CD8α+ DCs could not cross-present antigens to CD8+ T cells." (PMID 36552805, 2022). "Thus, we applied CD8+ T cell depletion in WT and mIgG2c-G400R mice by anti-CD8a antibody treatment before and during MC38 tumor model induction, and found that the enhanced antitumor effect of mIgG2c-G400R mice does depend on the normal function of CD8+ T cells to some extent." (PMID 35133976, 2022). "In one study of OSCC patient tumor samples, it was observed that the majority of intratumor tumor-infiltrating lymphocytes (TILs) were CD8+ T cells; this is consistent with the findings in our canine OSCC study where high CD3+T cell-infiltrated tumors had significant overexpression of CD8a." (PMID 36698398, 2022). "The quantity of tumor-infiltrating CD8+ T cells could be reflected by CD8A methylation, as significant correlations were revealed between higher CD8A methylation, lower CD8A mRNA expression, and fewer tumor-infiltrating CD8+ T cells in the TCGA-CHOL cohort." (PMID 35130881, 2022). "However, there did not appear to be a consistent trend when comparing tumor/normal by receptor subtype or PAM50 subtype for either GSAct or CD8A." (PMID 36376974, 2022). "In addition, many T cell signatures have been reported to be predictive for anti-PD1 response in a variety of tumor types, including cytolytic, T cell IFN-γ-related mRNA profiles, the chemokine CXCL9, CD8A, and an antagonistic inflammatory phenotype." (PMID 34534438, 2021). "Whereas naive mice could not control tumor growth after rechallenge, 7/9 mice previously treated with CD8α ALN-1 and CD13 AFR were protected." (PMID 34772757, 2021). "Importantly, the sustained peripheral TEG persistence was only observed for TEG011_CD8α but not TEGLM1_CD8α, highlighting the key role of a functional tumor-reactive γδTCR." (PMID 34759930, 2021). "Finally, 8 genes related to anti-tumor immunity were obtained, which were APOL3, CCL5, CD8A, CD8B, CXCL9, GZMA, GZMK and PRF1.We found that the m6A regulatory factors YTHDC1, YTHDC2, and WTAP were positively correlated with m6A, while IGF2BP3 was negatively correlated." (PMID 34737950, 2021). "We also found that GO-Y030 did not prevent CD8α+ cells from infiltrating into the tumor side." (PMID 34248973, 2021). "Importantly, enhanced tumor recognition was restricted to CD4+ TEG011_CD8α cells and not CD4+ TEGLM1_CD8α mock cells, highlighting the specific role of CD8α as co-stimulation for the introduced FE11 γδTCR." (PMID 34759930, 2021). "CD8A expression from tumors were also not correlated with autoreactive levels of CD8 T cells suggesting that T cells attracted to the tumor site by vem treatment are not tumor specific." (PMID 34210820, 2021). "Flow-cytometric analysis suggested that tumor progression (from days 11 to 25) results in increased frequencies of CD45+CD11chighCD11b−MHCIIhigh lymphoid-DC, with the majority of DCs exhibiting a CD8α+ phenotype and expressed a significant amount of cd3ε (C1, C2)." (PMID 32582141, 2020).